CD86 (CD86 molecule)
Diseases named in the same sentence as CD86 in open-access papers (continued):
Sharing a sentence is not in itself a finding about the gene and the disease.
allergic aspergillosis (1 paper, 2023). "Both CD86 and its paralog CD80 were upregulated in a model of experimental allergic aspergillosis, demonstrating a significant role for these co-stimulatory molecules in onset, persistence, and progression of immune responses." (PMID 37277347, 2023).
amyloid (1 paper, 2024). "Compared with controls, Aβ CAR-Ms upregulated CD86, MHC-II, CD40, and PD-L1 and downregulated CD206 after coincubation with amyloid-laden brain slices." (PMID 38516884, 2024).
anaemia (1 paper, 2012). "The multivariate model showed that the risk of anaemia at delivery was associated with a higher frequency of monocytes overall and of monocytes expressing high levels of CD86 amongst PBMC at inclusion." (PMID 23239967, 2012).
anaphylaxis (1 paper, 2019). An acute hypersensitivity reaction that occurs from exposure to an allergen. "Moreover, the SAV also disturbs various immunological parameters including expression of PMNs, CD-80, CD-86, interleukins and other cytokines compromising the affected organism towards mild to severe allergic reactions including life-risking anaphylaxis." (PMID 31847893, 2019).
ANCA-associated vasculitis (1 paper, 2023). "Further, mechanistic studies in ANCA-associated vasculitis identified CD28null T cells acting independently of the CD28/CD80 pathway, which may explain why CD80/CD86 inhibition in ANCA disease may not be optimal." (PMID 36598752, 2023).
angina (1 paper, 2014). "We found that the expression of CD86 on PBMCs was elevated at different times in response to LDL in all patients, particularly in the PBMCs from patients with recurrent angina or restenosis at follow-up (24.94% [0.89-91.63%]), compared to the patients without recurrent events (18.40% [5.71-55.10%])." (PMID 25253465, 2014).
anxiety disorder (1 paper, 2025). A category of psychiatric disorders which are characterized by anxious feelings or fear often accompanied by physical symptoms associated with anxiety. "This suggests that CORT, inflammatory factors (IL-6, IL-1β, CD86, TNF-α, TGF-β, IL-10), 5-HT, and GABA may serve as biomarkers for anxiety disorders." (PMID 40078708, 2025).
aortic aneurysm (1 paper, 2025). A ruptured aneurysm located in the wall of the proximal portion of the descending aorta proceeding from the arch of the aorta. "H3K18 lactylation (H3K18la) and M1 macrophage marker CD86 were upregulated and co-localized in the aortic aneurysm of AAA mice." (PMID 41213933, 2025). "The IF analysis revealed upregulated levels of H3K18la and increased CD86 expression in the AAA group, and H3K18la co-localized with CD86 in the aortic aneurysm, suggesting both an expansion of M1 macrophages and enhanced H3K18la levels within these M1 macrophages during AAA pathogenesis." (PMID 41213933, 2025).
apical periodontitis (1 paper, 2024). "Notably, the infiltration of the M1 sub-type Mφs (CD86+), M2 sub-type Mφs (CD163+) and M1/M2 ratio in apical periodontitis was significantly higher than that in the Cont group." (PMID 38612664, 2024).
arterial disease (1 paper, 2024). "For example, CD80/CD86 co-stimulation plays a role in promoting graft arterial disease after heart transplantation." (PMID 39926714, 2024). "Blocking CD80/CD86 at a later stage or selectively blocking CD80 alone can reduce the progression of graft arterial disease, but early graft loss was not prevented by CD80 blockade alone, unlike the more effective CD80/CD86 double blockade." (PMID 39926714, 2024).
arteritis (1 paper, 2025). An inflammatory process affecting an artery. "Specifically, CD4+ T cells are triggered by class-II major histocompatibility complex (MHC-II) and co-stimulatory molecules (CD80 and CD86), then infiltrated all the layers of the artery, leading to pan-arteritis." (PMID 39762453, 2025).
aspergillosis (1 paper, 2017). Aspergillosis is an infection, growth, or allergic response caused by the Aspergillus fungus. "Interaction of CD28 on T-cell surface with its ligand CD80 (B7-1) or CD86 (B7-2) on APCs and OX40 with OX40L has been shown to contribute to the immunological process of allergic forms of aspergillosis." (PMID 29371571, 2017).
atrial fibrillation (1 paper, 2023). A disorder characterized by an electrocardiographic finding of a supraventricular arrhythmia characterized by the replacement of consistent P waves by rapid oscillations or fibrillatory waves that vary in size, shape and timing and are accompanied by an irregular ventricular response. "A study based on human cardiomyocytes suggests that M1 macrophages with high expression of CD86 in atrial fibrillation may promote extracellular matrix remodeling of atrial fibroblasts and participate in the occurrence of atrial fibrillation." (PMID 36671813, 2023).
B-cell lymphopenia (1 paper, 2021). "Patients with kidney transplantation had B-cell lymphopenia, an impairment in co-stimulatory (CD86) and adhesion (CD54) molecules in monocytes, and a reduction in endothelium-derived microvesicles in plasma." (PMID 34646838, 2021). "The patients with KT showed B-cell lymphopenia, an increased proportion of T-cytotoxic lymphocytes, and increased levels of adhesion (CD54) and co-stimulatory (CD86) molecules in all monocyte subsets." (PMID 34646838, 2021).
B-cell neoplasm (1 paper, 2019). A group of heterogeneous lymphoid tumors generally expressing one or more B-cell antigens or representing malignant transformations of B-lymphocytes. "The effective communication between two subsets of co-stimulatory molecules of neoplastic B cells, CD80 (B7.1) and CD86 (B7.2), and the CD28 or cytotoxic T-lymphocyte–associated antigen 4 (CTLA-4) of T cells, is thought to play important roles in the tumorigenesis of B cell neoplasms." (PMID 30999581, 2019).
Ba (1 paper, 2022). "Particularly, we previously published results showing that Ba infection induces DCs maturation, as evidenced by the up-regulation of CD86, CD80, CCR7, CD83, MHC-II, MHC-I and CD40 at 24 h post-infection." (PMID 36441810, 2022).
brain inflammation (1 paper, 2023). "To detect brain inflammation, we used CD86 as a marker of M1 microglia and CD206 as a marker of M2 microglia." (PMID 37567914, 2023).
cardiomyopathy (1 paper, 2018). A disease of the heart muscle or myocardium proper. "Furthermore, only CD86 was associated with Treg cells, while CD80 showed a negative correlation with these regulatory cells only in the groups without cardiomyopathy (NI and IND)." (PMID 29599775, 2018).
carotid atherosclerosis (1 paper, 2021). A thickening and loss of elasticity of the walls of carotid arteries that occur with formation of atherosclerotic plaques. "NCF2, IQGAP2, and CD86 might play crucial roles in the process of carotid atherosclerosis." (PMID 33613306, 2021).
chronic hepatitis C (1 paper, 2008). "It has been reported that IFN-alpha can significantly enhance CD86 expression on dendritic cells from chronic hepatitis C patients." (PMID 18691426, 2008).
chronic renal failure (1 paper, 2021). "Some studies did not report changes in the expression of CD86 in monocytes of patients with chronic renal failure, whereas others showed a decrease in its expression in monocytes and dendritic cells of patients undergoing dialysis." (PMID 34646838, 2021).
cryptococcal infection (1 paper, 2018). "The IL-17−/− mice have reduced expression of MHC II, CD80 and CD86 on DCs at 4–8 weeks post-cryptococcal infection compared to WT mice." (PMID 29543719, 2018). "Scavenger receptor A (SRA)−/− mice have an increased accumulation of DCs in the lungs during cryptococcal infection, and these DCs have enhanced surface expression of co-stimulatory molecules CD80 and CD86, which leads to improved fungal clearance." (PMID 29543719, 2018). "Impaired accumulation of lung DCs occurs during cryptococcal infection in MARCO−/− mice, and these DCs have decreased expression of CD206, but increased expression of the costimulatory molecules CD80 and CD86." (PMID 29543719, 2018).
cryptogenic organizing pneumonia (1 paper, 2018). Cryptogenic organizing pneumonia (COP) is a form of idiopathic interstitial pneumonia characterized pathologically by organizing pneumonia (OP) that presents with non-specific flu-like symptoms, as well as cough and dyspnea and where no etiological agent is found. "In comparison, in bronchiolitis obliterans organizing pneumonia (now known as cryptogenic organizing pneumonia), an idiopathic interstitial lung disease believed to be secondary to epithelial damage, CD80 is upregulated in AECs without concurrent upregulation of CD86 or MHC class II expression." (PMID 30319613, 2018).
demyelinating polyneuropathy (1 paper, 2018). Polyneuropathy that is characterized by demyelination of axons. "Compared to two control strains, knockout of CD86 in NOD mice (CD86−/− NOD) resulted in progressive paralysis with distinct locomotor deficits due to a severe sensory-motor axonal-demyelinating polyneuropathy as assessed by electrophysiological measurements." (PMID 29618748, 2018).
demyelination (1 paper, 2019). "The Arg1+Iba1+ cells were restricted to the demyelination lesion core and surrounded by other Iba1+ cells like CD86+Iba1+ cells at 10 dpi, consistent with the localization of CD206+Iba1+ and CD16/32+Iba1+ cells at 10 dpi." (PMID 31623610, 2019). "Considering the distinct M/M polarization patterns between LPC- and LPS-induced demyelination, correlations between OD ratio and M1 (CD16/32+Iba1+ or CD86+Iba1+) and M2 (CD206+Iba1+ or Arg1+Iba1+) proportions were calculated in LPC and LPS groups, respectively." (PMID 31623610, 2019).
depression (1 paper, 2022). "An increase in TRAIL was observed in individuals with depression, in addition to an increased expression of CD14+CD86+." (PMID 36193083, 2022). "For the elderly with some level of depression, triple-positive cells for CD14+CD80+CD86+ showed a decreasing trend (p = 0.0611)." (PMID 36193083, 2022).
diabetic foot ulcer (1 paper, 2022). "Real-Time Polymerase Chain Reaction: RT-PCR for the gene expression of CD68, CD86, CD206, CD40, IL-6, IL-1β, and TNF-α revealed increased relative gene expression (normalized to housekeeping gene 18S) in diabetic foot ulcer tissues compared to control tissues." (PMID 36362563, 2022).
diarrhoea (1 paper, 2022). "The up-regulation of CD86 in diarrhoea-susceptible sheep suggests that its role is to enhance IL-4 production, promoting a Th2 immune response." (PMID 35576023, 2022). "Some of the DEGs in diarrhoea-susceptible sheep, enriched in GO terms and sub-network analysis, included IL-6, LOC101121216 (serum amyloid A), SIGLEC1, CHI3L1, S100A9, CD14, CD68, CD86, Ovar-DRB1, IL1RL1, LOC101103238 (CXCL5), CCL22 and IL1RN." (PMID 35576023, 2022).
diffuse midline glioma (1 paper, 2024). A diffuse glioma that arises from the midline structures of the central nervous system. "This hypothesis-generating study characterized the mRNA expression profiles and prognostic impacts of antigen-presenting cell (APC) markers (CD14, CD163, CD86, and ITGAX/CD11c) in pediatric brainstem diffuse midline glioma (pbDMG) tumors." (PMID 38255296, 2024).
dry eye (1 paper, 2021). "CD11c+CD86+ and CD11b+CD11c− cells are involved in experimental dry eye models." (PMID 34440626, 2021).
emphysema (1 paper, 2019). "Moreover, Th1 and Th17 cells, and CD40 and CD86 in the lungs of mice with emphysema positively correlated with the levels of extracellular DNA in BALF (r = 0.758, P = 0.011; r = 0.830, P = 0.003; r = 0.855, P = 0.002; r = 0.673, P = 0.033; respectively)." (PMID 31515489, 2019). "In vivo, erythromycin decreased NETs in the airway and ameliorated emphysema with Th1 and Th17 cell down-regulation and CD40+ and CD86+ mDCs suppression in mice chronically exposed to cigarette smoke." (PMID 31515489, 2019).
erythroleukemia (1 paper, 2023). Acute erythroid leukemia characterised by the presence of at least 50% erythroid precursors and at least 20% myeloblasts in the bone marrow. "Erythroleukemia cell line, HEL92.1.7 was treated for different durations (3–48 h) with the dual inhibitor and differentiation markers GFI1b, CD11b and CD86 were assessed." (PMID 36595522, 2023).
fertility disorder (1 paper, 2008). "CD86 expression on both mDCs and pDCs was found to be lower in Chlamydia positive women with or without fertility disorder, compared to controls but the difference was not significant." (PMID 18828896, 2008).
glomerulonephritis (1 paper, 2023). A renal disorder characterized by damage in the glomeruli. "It was also reported that the presence of CD86+ macrophages correlated with the severity of tubulointerstitial inflammation in human glomerulonephritis." (PMID 36831144, 2023).
Graves disease (1 paper, 2020). Graves' disease is an autoimmune disorder that leads to overactivity of the thyroid gland (hyperthyroidism).It is caused by an abnormal immune system response that causes the thyroid gland to produce too much thyroid hormones. "Flow cytometry analysis in blood of patients with early onset Graves’ disease and HT detected increased CD86 expression in thyroid-reactive B cells." (PMID 32603365, 2020).
Hernia (1 paper, 2023). "Furthermore, quantification of the M1 (CD86) and M2 (CD163) macrophage subsets indicate a predominance of M1 macrophages within the hernia, with no statistical difference in the M2/M1 ratio between the groups L6w and Mac6w." (PMID 37429889, 2023).
Hydrocephalus (1 paper, 2023). Hydrocephalus is an active distension of the ventricular system of the brain resulting from inadequate passage of CSF from its point of production within the cerebral ventricles to its point of absorption into the systemic circulation. "Therefore, the hydrocephalus phenotype affected the presence of CD86+ microglia in white matter (Two-way ANOVA, main factor “genotype” F = 9.434, **p = 0.0078)." (PMID 37296418, 2023).
immunotoxicity (1 paper, 2020). "The lower levels of CD80+ and CD86+ expressions in peripheral blood lymphocytes in our BIAA model were in agreement with a report study which showed that BZ-induced immunotoxicity could be due to lower levels of CD80+ and CD86+." (PMID 32256652, 2020).
inflammatory demyelinating neuropathy (1 paper, 2018). "Spontaneous autoimmune peripheral polyneuropathy (SAPP) is a reproducible mouse model of progressive inflammatory demyelinating neuropathy with secondary axonal loss in female nonobese diabetic (NOD) mice deficient in the costimulatory molecule, B7-2 (CD86)." (PMID 29615658, 2018).
inflammatory skin disease (1 paper, 2022). Inflammatory skin disorders covers a broad category that includes many conditions ranging in severity, from mild itching to grave medical health complications These disorders are common in people of all ages and races. "Importantly, given the lack of CD86 and CD80 expression in KCs, our study indicates new therapeutic options for inflammatory skin diseases, targeting CD6 directly in the skin rather than using systemic routes." (PMID 36353616, 2022).
interstitial lung disease (1 paper, 2022). A diverse group of lung diseases that affect the lung parenchyma. "Another study has reported circulatory macrophage (CD204+CD163+CD206+TLR4+CD80+CD86+) and monocyte (CD14+CD206+CD163+CD204+TLR4+CD80+CD86+) populations that expressed both M1/M2 markers in systemic sclerosis patients and in interstitial lung disease (ILD)." (PMID 35603185, 2022).
ischemic cardiomyopathies (1 paper, 2021). "However, as it was shown that the majority of heart resident human CD68+ macrophages co-express CD14 in dilated and ischemic cardiomyopathies, we applied CD86 and CD163 as additional markers for M1 and M2 macrophages, respectively." (PMID 33432417, 2021).
keloid (1 paper, 2022). An irregularly shaped, elevated mark on the skin caused by deposits of excessive amounts of collagen during wound healing. "The expression of costimulatory molecules (CD28, CD80, CD86 and CD40L) in the immune microenvironment of keloids is higher than that in healthy people." (PMID 36012134, 2022). "Our results may suggest that the abnormal expression of costimulatory molecules (including CD28, CD86, CD80 and CD40L) may exist in the skin tissue of patients with keloids." (PMID 36012134, 2022).
Kidney Cyst (1 paper, 2023). Abnormal fluid filled sac within the kidney, either acquired or congenital. "Here, we explored the contribution of 2 immune checkpoints, PD-1|PD-L1 and CTLA-4|CD80/CD86, to kidney cyst growth using different orthologous ADPKD1 models with varying rates of PKD progression." (PMID 37345660, 2023).
kidney injury (1 paper, 2020). Trauma to the kidney. "Consistently, the mRNA expression levels of CD86 and iNOS, which were the biomarkers of M1 macrophages, followed a similar pattern, indicating that the M1 macrophages activation was associated with the state of kidney injury." (PMID 33324643, 2020).
kidney transplant (1 paper, 2022). A surgical procedure in which one or both kidneys from a donor are implanted into a recipient. "Five diagnostic genes were further identified, including CCR5, CD86, CD8A, ITGAM, and PTPRC, which were positively correlated with allograft rejection after the kidney transplant." (PMID 36330810, 2022). "In this study, CCR5, CD86, CD8A, ITGAM, and PTPRC were up-regulated and had the positive correlation with allograft rejection in kidney transplant patients." (PMID 36330810, 2022). "Thus, it can be seen that PTPRC, CD86, CCR5, and ITGAM could be considered as potential targets of PREDNISONE, EPOETIN BETA, ABATACEPT, MARAVIROC, and CLARITHROMYCIN, which may provide novel treatment options for kidney transplant patients with allograft rejection." (PMID 36330810, 2022).
Liver abscess (1 paper, 2021). A circumscribed area of pus or necrotic debris in the liver. "In addition, macrophages from the tissue with liver abscess (D27) showed the greatest CD86+ pro-inflammatory cell population of the investigated donors, at approximately 23%." (PMID 33918803, 2021).
liver disease (1 paper, 2013). "We also report for the first time that memory B cell CD86 expression levels and percentages of memory B cells expressing CD86 were significantly associated with advanced liver disease, whereas all other activation markers measured remained unchanged." (PMID 23840845, 2013). "In addition, we found that CD86 was specifically upregulated on memory B cells from HCV patients with advanced liver disease." (PMID 23840845, 2013).
lymphoid neoplasm (1 paper, 2021). A neoplasm composed of a lymphocytic cell population which is usually malignant (clonal) by molecular genetic and/or immunophenotypic analysis. "CD86 shows elevated expression in cluster 7 in comparison to the other clusters, which could not only indicate that CD86 is specific for lymphoid neoplasms, but also that the signaling pathway of CD86-CD28 is perturbed leading to CD28 stimulation." (PMID 34006939, 2021). "The lymphoid neoplasm samples in clusters 3 and 6 do not have an increased expression of both CD28 and CD86." (PMID 34006939, 2021).
mastocytoma (1 paper, 2014). A localized tumor composed of sheets of mast cells without atypia. "In our colleagues’ study, freshly isolated murine CD4+T cells were incubated with murine mastocytoma P815 cells transfectants expressing a similar level of either CD80 or CD86 in the presence of anti-CD3 mAb." (PMID 25344652, 2014).
Myocardial fibrosis (1 paper, 2021). "ICM mice had excessive myocardial fibrosis, hypertrophy, and aggravated LVSDs which were accompanied by massive CD86+ inflammatory cells infiltration." (PMID 34901202, 2021).
neuritis (1 paper, 2026). A neuropathy arising from inflammation of one or more nerves. "The role of the costimulatory molecule B7.2 (CD86) in the induction of neuritis has been demonstrated in experimental models." (PMID 41602156, 2026).